AR (androgen receptor)
Diseases named in the same sentence as AR in open-access papers (continued):
Sharing a sentence is not in itself a finding about the gene and the disease.
prostate carcinoma (continued). "Recently, we and others found that Vav3 oncogene is overexpressed in androgen-independent prostate cancer cells, enhances androgen receptor (AR) activity, and stimulates androgen-independent growth in prostate cancer cells." (PMID 18518979, 2008). "To further examine the effects of androgens on prostate cancer growth mediated by the Wnt and AR signaling, we took advantage of the stable LNCaP-Flag-AR cell line that overexpresses the wild-type AR mimicking the hormone -refractory state." (PMID 18218096, 2008). "Identification of androgen-regulated genes is essential to elucidate the AR pathophysiology in prostate cancer." (PMID 19468457, 2008). "It is up-regulated in prostate cancer cells when compared to normal adjacent tissue and its expression is regulated by the ligand bound androgen receptor (AR)." (PMID 18631392, 2008). "The AR protein can be detected even in the androgen-independent prostate cancer and AR signaling is believed to be important even in so-called "androgen independent disease"." (PMID 18986533, 2008). "Our data indicates that in hormone-refractory prostate cancer cells, the AR signals through the Wnt/β-Catenin pathway to promote tumor cell malignancy in a ligand-independent manner." (PMID 18218096, 2008). "Two genes that regulate prostate cancer progression by enhancing growth and blood supply, AR and VEGF, have multiple WT1 and SP1 binding sites in their proximal promoter regions." (PMID 18631392, 2008). "The androgen receptor signaling pathway has been shown to play an essential role in castration-refractory prostate cancer." (PMID 18218096, 2008). "Immunohistochemistry was employed to investigate the expression and phosphorylation status of Akt and AR in matched hormone-sensitive and -refractory prostate cancer tumours from 68 patients." (PMID 18349820, 2008). "Our previous study suggests that LXR, VDR and androgen receptor (AR) signaling form a complex interaction in the prostate cancer LNCaP cells." (PMID 19787078, 2008). "Studies of cultured prostate cancer cells show an inhibitory effect of Se on AR gene expression and various mechanisms have been proposed." (PMID 19025659, 2008). "In this report, we employed ChIP-chip to map the locations of both the AR and AcH3 onto 3% of the genome in C4-2B prostate cancer cells." (PMID 18997859, 2008). "Since androgen- and androgen receptor (AR)-mediated signalling are often essential for the initiation and progression of prostate cancer, targeting the receptor and/or its signalling pathways represents a rational strategy for treating this disease." (PMID 18253123, 2008). "Recent emerging evidence indicates that the Wnt/β-Catenin signaling pathway is involved in advanced prostate cancer, and it is known that β-Catenin can signal through the AR in the presence of androgens." (PMID 18218096, 2008). "The critical role of the androgen receptor (AR) in the development of prostate cancer is well recognized." (PMID 18673534, 2008). "Transient transfections of several human prostate cancer cell lines with the AR and multiple components of the Wnt signaling pathway demonstrate that the AR overexpression can potentiate the transcriptional activities of Wnt/β-Catenin signaling." (PMID 18218096, 2008). "In sum, our finding provides a novel mechanism of the AR function, namely, promoting Wnt/β-Catenin signaling and its resulting oncogenic properties in prostate cancer cells at castration levels of androgens." (PMID 18218096, 2008). "It has been experimentally shown that overexpression on AR is required and it is sufficient to transform the growth of prostate cancer cells from androgen-dependence to -independence." (PMID 18673534, 2008). "The androgen receptor (AR) is a ligand-regulated modular nuclear receptor governing prostate cancer cellular proliferation, differentiation, and apoptosis in response to androgens." (PMID 21566744, 2008).
prostate carcinoma (continued). "In prostate cancer, ectopic expression of Ebp1 results in downregulation of Androgen Receptor (AR) and several of its target genes and inhibition of AR-regulated cell growth." (PMID 19094237, 2008). "Since androgens and AR are known to be important in the prostate cancer tumorigenesis, it is possible that they also regulate the expression of the coregulators." (PMID 18673534, 2008). "Prostate cancer is an hormone-dependent tumour in which androgen receptor activity is related to the expression of PSA (prostate specific antigen) as well as to other cancer-associated npcRNAs (DD3, PCGEM1)." (PMID 18631387, 2008). "In hormone-sensitive prostate cancer cells, the androgen-bound AR can inhibit the Wnt/β-Catenin signaling." (PMID 18218096, 2008). "Those conditions revealed a strong nuclear AR staining in prostate cancer cells with Gleason Score (GS) 6 and above." (PMID 18218096, 2008). "This agrees with past reports that the AR overexpression increased the oncogenic malignancy and transformation of prostate cancer cells." (PMID 18218096, 2008). "Previous studies from our group have demonstrated that Vav3 is overexpressed in human prostate cancer and potentiates AR signaling." (PMID 18518979, 2008). "The analyses revealed that BPA exposure in cells expressing AR-T877A triggers a dramatic reduction in expression of ERβ, a nuclear receptor suspected to negatively regulate both AR activity and prostate cancer cell proliferation." (PMID 18007998, 2007). "Upregulation of AR in all samples from metastatic cancer patients represents a known "androgen resistant" or AARPC (androgen ablation resistant prostate cancer) phenotype." (PMID 17430594, 2007). "The second data set consisted of differentially expressed genes following androgen receptor stimulation in a prostate cancer cell line." (PMID 17233900, 2007). "Some of the genes near AR-occupied regions appear to be regulated by the AR in vivo as evidenced by their expression levels in prostate cancer tumors of various stages." (PMID 17553165, 2007). "Microarrays have been used to study androgen regulated genes involved in the development of prostate cancer, and to characterize molecular function of AR or other steroid receptor interacting proteins." (PMID 17553164, 2007). "The role of AR in androgen-dependent prostate carcinomas has been well established over years, and recently confirmed using an inducible AR-shRNA lentiviral construct in LNCaP tumors." (PMID 17925854, 2007). "Among the hormone and DDC down-regulated genes was the SYTL2 gene, which was previously shown to be positively regulated by AR reduction in androgen-ablated prostate cancer cells." (PMID 17553164, 2007). "Given the importance of androgen action and AR function in prostate cancer growth and progression, much emphasis has been devoted to delineating the mechanisms by which AR promotes tumour cell proliferation and the factors that govern these events." (PMID 17375037, 2007). "Our laboratory has shown that DDC is a coactivator of AR and a neuroendocrine marker of prostate cancer that increases in expression during hormone-ablation therapy and after progression to AI." (PMID 17553164, 2007). "A role for AR-mediated gene activation in recurrent prostate cancer is supported by its expression together with the expression of androgen-regulated genes." (PMID 17367528, 2007). "Since the ARR2PB promoter is known to be inducible by androgen (e.g., dihydrotestosterone; DHT), the LNCaP cell line was chosen specifically because it is one of the few prostate cancer cell lines available that express functional androgen receptor (AR)." (PMID 17295927, 2007). "The second data set consisted of a list of differentially expressed genes following the agonistic stimulation of the androgen receptor in a prostate cancer cell line." (PMID 17233900, 2007). "Cyclin D1 has the potential to regulate both cellular proliferation and AR-dependent transcription in prostate cancer cells." (PMID 17375037, 2007).
prostate carcinoma (continued). "The CBP has been shown to enhance the agonistic properties of flutamide, increasing AR transactivation in the prostate cancer cell lines LNCaP and DU145." (PMID 19675761, 2007). "This was in contrast to the predominant cytosolic distribution of AR in androgen-deprived prostate cancer cells." (PMID 17986353, 2007). "Overexpression of AR increases the sensitivity of prostate cancer cells to low levels of androgens, which promotes androgen-independent growth." (PMID 17262078, 2007). "Consistent with our observation in breast cancer cell lines, it appears that basal-type prostate cancer cells expressing low levels of AR and PSA and a high level of CK5 are most responsive to dasatinib treatment." (PMID 18047674, 2007). "Increasingly, clinical observations demonstrate that in the majority of castration-resistant prostate carcinomas (CRCaP, also called hormone-refractory), AR is expressed and controls transcription." (PMID 17925854, 2007). "The androgen receptor is a ligand-induced transcriptional factor, which plays an important role in normal development of the prostate as well as in the progression of prostate cancer to a hormone refractory state." (PMID 17553164, 2007). "Studies also showed that AR, as a crucial factor, determines the molecular alterations required for the development of refractory prostate cancer." (PMID 17262078, 2007). "We used in this study RNA interference to investigate in vitro and in vivo the function of AR in prostate carcinomas." (PMID 17925854, 2007). "Our study implies that high doses of PL are able to elicit multiple apoptotic signalling pathways in prostate cancer cells, and that caspase 2, acting downstream of the AR, sensitises prostate cancer cells to PL-induced apoptosis." (PMID 17262078, 2007). "While the cell lines considered here were entirely androgen pathway independent, other prostate cancers develop hypersensitivity to androgen receptor pathway signaling; this latter type of hormone therapy resistant cancer was not considered in this study." (PMID 17598908, 2007). "There is also evidence that despite castration, both surgical and medical, the prostate retains a level of androgen that is high enough to induce AR transactivation in prostate cancer cell lines." (PMID 19675761, 2007). "A role for AR in prostate cancer progression is supported by the correlation between its overexpression and the expression of androgen-regulated genes." (PMID 17384772, 2007). "Possible mechanisms for AR reactivation in recurrent prostate cancer include altered growth factor-induced phosphorylation and AR mutations that broaden ligand specificity." (PMID 17367528, 2007). "A recent study in prostate cancer cell lines showed that an HER2/ERBB3 signalling pathway protected the AR from degradation by the ubiquitin–proteasome pathway and enhanced AR transcriptional activity at low androgen concentrations." (PMID 17211467, 2007). "Our results here demonstrate the interconnection between AR and caspase 2 in the regulation of PL-induced apoptosis in prostate cancer cells." (PMID 17262078, 2007). "The impact of BPA exposure on ERβ transcript was examined further in the LAPC4 prostate cancer cell line, which harbors wild-type AR and is androgen dependent." (PMID 18007998, 2007). "The AR gene expression in prostate cancer progression occurs through different mechanisms including amplification, mutations, and ligand-independent activation." (PMID 19936097, 2007). "BPA and DHT elicited distinct transcriptional signatures in prostate cancer cells expressing the BPA-responsive mutant AR-T877A." (PMID 18007998, 2007). "We all know that prostate cancer is androgen-sensitive in the initial stage and depends on the androgen receptor (AR) to mediate the effects of androgens." (PMID 19675760, 2007). "The molecular signature of BPA activity in prostate cancer cells harboring mutant AR was delineated via genetic microarray analysis." (PMID 18007998, 2007).
prostate carcinoma (continued). "Although these reports highlighted a potentially influential role of BPA on ER activity in breast cancer, recent studies reveal BPA as an agonist for mutant androgen receptor (AR) activity in recurrent prostate cancer." (PMID 18007998, 2007). "SYTL2 was among the androgen down-regulated genes, and has been previously shown to be differentially regulated by AR reduction in prostate cancer cells." (PMID 17553164, 2007). "Given the potent effects of BPA on mutant AR activation and prostate cancer progression, it is imperative to determine the molecular underpinning of BPA action." (PMID 18007998, 2007). "This fortifies the concept that events downstream of AR are of critical importance to arsenic-induced prostate cancer progression." (PMID 17384772, 2007). "In prostate cancer, a number of studies have indeed shown methylation in the promoter region of the AR leading to its inactivation; however, the frequency of methylation seems to be low." (PMID 19936097, 2007). "High levels of AR can correlate with prostatic cancer progression in many cases, and AR gene amplification is observed in 20–30% of all hormone-refractory prostate cancers." (PMID 17384772, 2007). "Changes in the androgen receptor (AR) have been indicated to contribute to the development of prostate cancer and are a serious challenge to effective treatment." (PMID 17262078, 2007). "Given the critical importance of controlling AR activity for prostate cancer therapy, the present study provides the foundation for future investigations directed at dissecting the role of BPA and ERβ in controlling prostate cancer growth and/or progression." (PMID 18007998, 2007). "As such, first line therapy for disseminated prostate cancer entails ablation of AR activity, either through deprivation of ligand or through the use of direct AR antagonists." (PMID 17375037, 2007). "With the progression of the degree of the malignancy, prostate cancer loses expression of AR and abrogates the hormone dependency." (PMID 17262078, 2007). "Prostate cancer is initially androgen dependent and relies upon the androgen receptor (AR) to mediate the effects of androgens." (PMID 19675761, 2007). "Expression of RAC-3 (also known as SRC-3) was higher in prostate cancer cell lines expressing the AR and has been shown to promote ligand-independent activation of the Akt pathway." (PMID 19675761, 2007). "The repressor functions occur at stoichiometric levels of AR and cyclin D1, thus indicating that modest elevations of cyclin D1 can have significant effects on prostate cancer growth." (PMID 16863592, 2006). "The loss AR expression occurs in several prostate cancer cell lines, such DU145, PPC1 and PC3, and occurs frequently during the clinical evolution of prostate cancer." (PMID 16774685, 2006). "Prostate cancer cells are unique amongst tumors types in that they are dependent on AR function for growth and survival." (PMID 16863592, 2006). "In prostate cancer, the disparate ability of cyclin D1b to govern AR function appears to hold significance for both the control of transcriptional regulation and cellular proliferation." (PMID 16863592, 2006). "Together, these observations indicate that AR is a critical determinant for prostate cancer growth and progression." (PMID 16863592, 2006). "To begin addressing these questions we tested the effect of C/EBPα expression on AR and PSA expression in LNCaP cells, a prostate cancer cell line that expresses both AR and PSA." (PMID 16774685, 2006). "The PI3K pathway appears to be critical in the development of CRPC: in vitro data suggest that overexpression and activation of AKT can trigger prostate cancer androgen escape via altered sensitivity and activation of AR." (PMID 16983403, 2006). "In prostate cancer, Akt has been shown to modulate by phosphorylation the activity and stabilisation of the nuclear androgen receptor." (PMID 16721361, 2006).
prostate carcinoma (continued). "AR gene amplification and overexpression can make cells hypersensitive to low levels of androgen, and many prostate cancers show overexpression of AR." (PMID 16140617, 2005). "We have recently identified a membrane androgen receptor site on prostate carcinoma cells, mediating testosterone rapid effects on the cytoskeleton and secretion within minutes." (PMID 16293185, 2005). "Prostate cancer therapy often involves orchiectomy and pharmacologic intervention to diminishing availability of androgen at the androgen receptor (AR) within prostate cancer cells." (PMID 16140617, 2005). "As the complement of coregulators in different cells are important for AR activity, we determined the effect of Ebp1 on AR function in prostate cancer cell lines." (PMID 15583694, 2005). "In prostate cancer epithelial nuclei, African Americans exhibited 38% higher levels of AR immunostaining than Caucasian Americans (two sided Student's t-tests; P < 0.05)." (PMID 15888205, 2005). "The differences measured in the intensity of AR expression in prostate cancer were consistent with previous studies." (PMID 15888205, 2005). "Altered AR levels or activity can be key elements in acquired androgen independence in prostate cancer." (PMID 16140617, 2005). "Initially, prostate cancers are androgen-sensitive (that is, they cease growing when deprived of androgens or when treated with androgen receptor antagonists, such as flutamide or bicalutamide), and therefore most patients respond to androgen ablation therapy." (PMID 15647107, 2005). "The potential role of the epidermal growth factor (ErbB) family of receptors and their ligands in regulating AR activity during prostate cancer progression is currently a focus of intense investigation." (PMID 15583694, 2005). "An extensive body of work demonstrating cross talk between ErbB receptors and their ligands and the AR in prostate cancer has evolved." (PMID 15583694, 2005). "The expression of AR in paired specimens of benign prostate and prostate cancer from 20 African and 20 Caucasian Americans was compared to demonstrate an application of this system." (PMID 15888205, 2005). "Further studies are needed to characterise the interactions of ErbB3, Ebp1 and AR in the progression of prostate cancer." (PMID 15583694, 2005). "Androgen receptor expression in benign prostate and prostate cancer tissue specimens from 20 African Americans and 20 Caucasian Americans." (PMID 15888205, 2005). "Prostate cancer cells can achieve functional AR signaling in the presence of greatly diminished androgens in a variety of ways." (PMID 16140617, 2005). "In this study, we demonstrate, using several natural AR-regulated promoters, that Ebp1 repressed transcriptional activation of wild-type AR in prostate cancer cell lines." (PMID 15583694, 2005). "In many instances of acquired androgen independence in prostate cancer, the AR is modified such that it becomes sensitive to a variety of steroids, including nonandrogens." (PMID 16140617, 2005). "AR expression or ligand specificity played a minimal role in this arsenic-induced prostate cancer cell progression." (PMID 16140617, 2005). "Androgen withdrawal led to transcriptional downregulation of the pyruvate dehydrogenase E1 alpha (PDH E1α) gene in rat ventral prostate and in PC3 prostate cancer cells transiently transfected with the androgen receptor." (PMID 15790394, 2005). "A preliminary study comparing AR expression in paired specimens of benign prostate and prostate cancer from 20 African and 20 Caucasian Americans is presented to demonstrate an application of this system." (PMID 15888205, 2005). "Drugs that directly interfere with coactivator binding or formation of the AR N/C interaction would likely inhibit AR activity, perhaps even in androgen-resistant prostate cancers in which conventional therapies have failed." (PMID 15328534, 2004).